PRL (prolactin)
Diseases named in the same sentence as PRL in open-access papers (continued):
Sharing a sentence is not in itself a finding about the gene and the disease.
atherosclerosis (continued). "On the other hand, prolactin retention can inhibit the production of gonadotropic hormone, and consequently induce a testosterone deficiency in male patients with CKD, and through this mechanism, atherosclerosis." (PMID 37510208, 2023). "Prolactin plays a role in the proliferation of vascular smooth muscle cells, and the proliferation of vascular smooth muscle cells is a characteristic of cardiovascular diseases such as hypertension and atherosclerosis." (PMID 36358920, 2022). "Meanwhile, prolactin has been suggested to stimulate the development of atherosclerosis and cardiovascular disease through its effects on metabolism and inflammation, and the inhibition of prolactin function may beneficially affect atherosclerosis burden." (PMID 35990823, 2022). "Prolactin can induce smooth muscle cells growth through a mechanism that depends on protein kinase C and may also play a role in the hyperplasia of muscle cells of the arteries and lead to atherosclerosis." (PMID 32303254, 2020). "KEGG analysis showed that NDEGs were mainly enriched in MAPK signaling pathway, lipid and atherosclerosis, mTOR signaling pathway, JAK-STAT signaling pathway, prolactin signaling pathway, glycerophospholipid metabolism and other pathways." (PMID 40433461, 2025). "KEGG analysis revealed that these NDEGs were primarily enriched in pathways such as the PI3K-Akt signaling pathway, MAPK signaling pathway, lipid and atherosclerosis, JAK-STAT signaling pathway, and prolactin signaling pathway, among others." (PMID 40433461, 2025). "ED has been related with hemodynamic status and seems to display peripheral vessel rheology, even in patients with atherosclerosis and CHF, while the role of serum prolactin role is still debated in CHF mechanisms is still under consideration." (PMID 33396861, 2020). "The top 10 KEGG pathways include: Pathways in cancer, Lipid and atherosclerosis, Efferocytosis, Coronavirus disease-COVID-19, IL-17 signaling pathway, Endocrine resistance, MAPK signaling pathway, Prolactin signaling pathway, Non-alcoholic fatty liver disease, Colorectal cancer." (PMID 41244831, 2025). "We consider that the migraine patients are prone to subclinical atherosclerosis, but this tendency is independent of prolactin levels." (PMID 21331754, 2011). "Sauro and Zorn49 found that PRL‐induced aortic smooth muscle cell proliferation is mediated through PKC pathway, suggesting the role of PRL in vascular smooth muscle cell hyperplasia and the pathogenesis of cardiovascular diseases such as hypertension and atherosclerosis." (PMID 35923071, 2023).
Hypertension (36 papers, 2013 to 2026). The presence of chronic increased pressure in the systemic arterial system. "One of them, prolactin, a polypeptide hormone of lactation, exerts pleiotropic cytokine effects that are associated with hypertension and cardiac remodeling." (PMID 38672089, 2024). "Biological pathways that were downregulated in male CIH animals are also associated with hypertension and autonomic dysfunction: Nitric Oxide Signaling in the Cardiovascular System, and Prolactin Signaling." (PMID 38981849, 2024). "Elevated serum prolactin has been associated with the development of hypertension through a reduction in endothelial nitric oxide synthase activity in mice." (PMID 38672089, 2024). "Cases of intracranial hemorrhage and an increased risk of postpartum hypertension due to drug-induced hypertension have been reported for prolactin inhibitors (bromocriptine, cabergoline)." (PMID 38694908, 2024). "Variations in the expression of genes implicated in this system, such as PRL, have been linked to an increased risk of hypertension." (PMID 37571339, 2023). "In humans, two studies have shown that increased levels of PRL were associated with elevated arterial pressure in women with hypertension and normotensive pregnant women." (PMID 36704037, 2022). "Recently, a cohort study has demonstrated that a higher daytime plasma PRL level, even within the normal range, was associated with an increased risk of incident hypertension among postmenopausal women from the Nurses’ Health Study." (PMID 36704037, 2022). "Prolactin has been linked to the pathogenesis of pregnancy-associated hypertension by modulating the activity of endothelial nitric oxide synthase." (PMID 35885604, 2022). "Moreover, diurnal fluctuations in PRL levels were significantly associated with hypertension in men." (PMID 38398117, 2024). "Likewise, reduced Prolactin Signaling and Nitric Oxide Signaling in the Cardiovascular System pathway activity is associated with autonomic dysfunction, hypertension, and cardiovascular disease." (PMID 38981849, 2024). "This may be because each 5 mg/dL increase in PRL, even at normal levels, is associated with a significant increase in hypertension." (PMID 38398117, 2024). "Previous studies have implicated high prolactin (PRL) levels with consequent hypertension." (PMID 38034389, 2023). "Indeed, the link between AP use and increased PRL has been well-established, and high PRL has been associated with hypertension." (PMID 35546954, 2022). "Conditions such as gestational diabetes, hypertension, hyperkalemia, abnormal prolactin, hypocalcemia, diabetic ketoacidosis, low calcium, magnesium, or phosphate, and low vitamin D each accounted for 1.79% (n=1)." (PMID 40799873, 2025). "Prolactin was statistically significantly lower in the hypertension group [median (25th–75th percentile): 10.51 (4.72; 17.5)] compared to patients without hypertension [21.5 (13.71; 36.23), p < 0.001]." (PMID 40650124, 2025). "When dopamine synthesis decreases, prolactin levels increase, which in turn increases sympathetic tone and promotes the development of hypertension." (PMID 40650124, 2025). "Animal studies have shown that high PRL levels exert positive chronotropic and vasoconstrictive effects, which induce hypertension." (PMID 38398117, 2024). "At T2, RS correlated negatively and significantly with age (r = −0.497, P = 0.04), with BDI-II score (r = −0.4692, P = 0.049), and with duration of hypertension (r = −0.926, P = 0.0009), but trendwisely with baseline prolactin levels (r = −0.5845, P = 0.06)." (PMID 31336717, 2019). "Cord blood prolactin is significantly higher in pregnancies complicated by hypertension than uncomplicated pregnancies, pregnancies with gestational diabetes and preterm labours." (PMID 31372154, 2019).
Hypertension (continued). "Some studies found a positive association between serum PRL levels and metabolic parameters such as incident hypertension, waist circumference, aortic stiffness, and mortality, as seen in individuals with pathologically high serum PRL levels." (PMID 28384295, 2017). "Another reproductive peptide that warrants further investigation into its potential contribution to the pathogenesis of hypertension is prolactin, a hormone best known for its involvement in lactation and reproduction." (PMID 27092251, 2016). "Additionally, the levels of PRL and the PRL-E2/T ratio in women with hypertension in the 5 years since menopause group and those in the 6–10 years since menopause group were greater than those in their matched male counterparts (P < 0.05)." (PMID 41555389, 2026). "In women with hypertension in the 5 years since menopause group, the FSH/PRL ratio was independently associated with 24-h SBP, 24-h DBP, daytime SBP, daytime DBP, and nighttime DBP (P < 0.05), whereas the T/PRL ratio-E2 level was independently associated with nighttime SBP (P < 0.05)." (PMID 41555389, 2026). "Although these results suggest that high PRL levels are closely associated with hypertension, there is no direct data to show that prolactinoma is linked to hypertension." (PMID 38398117, 2024). "Evidence has shown that high levels of PRL may accelerate vascular aging in menopause and play a key role in increasing the prevalence of hypertension after menopausal transition." (PMID 34305584, 2021). "In normal pregnancy, the rise of maternal prolactin reaches 5–10 fold of its level in a non-normal state during the third trimester, and dysregulated maternal prolactin levels have been linked to pregnancy complications such as gestational diabetes and hypertension." (PMID 35885604, 2022). "This study investigated the association of postpartum maternal serum hormone levels of estradiol, progesterone, prolactin, and ß-HCG with poorer PE-related complications including arterial hypertension." (PMID 35885604, 2022). "The data revealed the laboratory characteristic with significant differences between the co-infected and non-co-infected groups for CKD, hypertension, haemoglobin, the PT measure, prolactin, LDH and ALT enzyme." (PMID 37630481, 2023).
endometriosis (35 papers, 2015 to 2025). The growth of functional endometrial tissue in anatomic sites outside the uterine body. "Further studies are needed to clarify the exact role of elevated PRL and PRL receptors as well as the associated mechanism in the pathogenesis of endometriosis and adenomyosis." (PMID 39407928, 2024). "An important question for clinical practice is the possible effects of elevated prolactin serum levels on pelvic pain associated with endometriosis." (PMID 39407928, 2024). "In thisinvestigation, we evaluated the association between serum prolactin levelsand the severity of endometriosis." (PMID 30969738, 2019). "Statistically significant associations were found between staging of endometriosis and prolactin levels (p=0.01)." (PMID 26000006, 2015). "Endometriosis, a chronic gynecological condition characterized by the presence of endometrial tissue outside the uterine cavity, has also been associated with elevated prolactin levels." (PMID 40656428, 2025). "There is also a question of whether prolactin serum levels are valid as diagnostic criterium for the presence of endometriosis as well as whether there are differences in the prolactin serum levels between stages of the disease." (PMID 39407928, 2024). "It was proposed that targeting prolactin and prolactin receptors may improve the management of the pain associated with endometriosis." (PMID 39407928, 2024). "The authors suggested that higher levels of serum prolactin may be associated with the progression of endometriosis." (PMID 33669013, 2021). "Some authors describedthat increases in baseline serum prolactin might have a causative role ininfertility affecting patients with severe endometriosis." (PMID 30969738, 2019). "By investigating a larger series of patients whencompared to the previous study, we also found a cutoff value that increases thechance of telling individuals with endometriosis from controls (PRL >17.5ng/mL).The strength of the association was clearly confirmed in effect size analysis." (PMID 30969738, 2019). "One way ANOVA was used to determine PRL association with endometriosis stages." (PMID 26000006, 2015). "In our opinion, the proposed panel of parameters, particularly IL-6, PRL and CA 125, could be a useful clinical tool to identify women with a high risk of endometriosis development, due to the enhanced expression of inflammatory biomarkers when compared to the healthy population." (PMID 33669013, 2021). "It is unclear whetherincreased prolactin levels are the cause or consequence of endometriosis." (PMID 30969738, 2019). "Given the elevated TNF-α levels in EPF, the addition of soluble TNF-α receptor 1 (sTNFR-1) partially rescued PRL secretion in eutopic (endometriosis) ESCs, suggesting that TNF-α mediates the inhibitory effects of EPF." (PMID 40072055, 2025). "Collectively, these studies demonstrate impaired decidualization capacity in eutopic ESCs from endometriosis patients, characterized by reduced expression and secretion of the decidualization markers PRL and IGFBP1." (PMID 40072055, 2025). "The interaction between stress, prolactin, and endometriosis remains a topic of ongoing research, as stress can further disrupt hormonal balance and exacerbate symptoms." (PMID 40656428, 2025). "In this section, we focus on IGFBP1 and PRL expression dysregulation during the decidualization of ESCs from patients with endometriosis." (PMID 40072055, 2025). "Some studies have reported a positive correlation of the basal and stimulated prolactin serum levels with endometriosis and stages of the disease, but there have also been studies that failed to prove such connections." (PMID 39407928, 2024). "The results of studies on the possible connection and involvement of prolactin in the development of endometriosis are contradictory." (PMID 39407928, 2024).
endometriosis (continued). "The results of the clinical studies on the impact of prolactin lowering medication suggest the possible beneficial effects of dopamine agonists in endometriosis/adenomyosis." (PMID 39407928, 2024). "According to the reported studies, it seems that local prolactin, acting as an autocrine or paracrine factor, is more important in the development of endometriosis and adenomyosis than the prolactin serum levels." (PMID 39407928, 2024). "In patients with exaggerated PRL response to LHRH/TRH tests before the treatment of endometriosis, danazol treatment was less effective." (PMID 39407928, 2024). "The results of the studies on the effects of the treatment for endometriosis on the prolactin serum levels are also contradictory." (PMID 39407928, 2024). "The results of other experimental studies also support the role of local prolactin in the development of endometriosis." (PMID 39407928, 2024). "The results were similar to previous studies: the basal prolactin serum levels as well as prolactin response to TRH stimulation were higher in patients with endometriosis compared to the fertile controls." (PMID 39407928, 2024). "General blood tests, biochemical/hormone profiles and blood coagulation parameters were similar between the groups, except higher prolactin levels in patients with endometriosis (465.6 ± 299.4 vs. 255.4 ± 114.9; p < 0.001)." (PMID 38673823, 2024). "The results of other experimental studies also support the role of prolactin in the aetiology and pathogenesis of endometriosis." (PMID 39407928, 2024). "The correlation of the prolactin serum levels and severity of endometriosis is a clinically important question." (PMID 39407928, 2024). "The true mechanisms of action ofhyperprolactinemia in patients with endometriosis are still not fully understood.However, studies only suggested prolactin concentration progressively increased fromstage I to IV." (PMID 36350241, 2022). "On the other hand, the oscillations of FSH and prolactin levels varied in relation tothe stage of endometriosis progression." (PMID 36350241, 2022). "Therefore, in this study, we decided to examine whether selected parameters of inflammation (IL-1β, IL-6, hs-CRP, IgG, YKL 40 and PRL) could become a set of additional diagnostic markers (all of them or some of them) supporting the diagnosis of advanced endometriosis." (PMID 33669013, 2021). "The prolactin cut-off point proposed for endometriosis diagnostics in this study is 19.35 ng/mL, with a sensitivity of 60% and specificity of 94.4%." (PMID 33669013, 2021). "It was highlighted that despite the high specificity, the sensitivity of serum prolactin for the diagnosis of endometriosis remained unacceptably low." (PMID 33669013, 2021). "In women with endometriosis and serum PRL levels of greater than 30 ng/ml, quinagolide 25 to 75 μg/day has been found to reduce the surface of endometriotic lesions by 69.5% after 4 months of treatment." (PMID 33162942, 2020). "The pathogenesis of benign uterine diseases, including adenomyosis, leiomyomas and endometriosis, has been related to direct PRL effects." (PMID 33162942, 2020). "CA125, FSH, and prolactin levels were significantly higher in women with endometriosis compared with the control group." (PMID 32751449, 2020). "Both IGFBP-1 and PRL are drastically downregulated in the eutopic endometrium of women affected by endometriosis." (PMID 32063886, 2019). "The prognostic capability of prolactin in detecting endometriosis stagesIII/ IV vs. stages I/II was analyzed by ROC curve analysis." (PMID 30969738, 2019). "Prolactin values with a cut off set at 17.5 ng/mL had asensitivity of 0.64 and specificity of 0.63 in segregating subjects with andwithout endometriosis." (PMID 30969738, 2019). "Prolactin levels of 17.5 ng/mL had a sensitivity of0.64 and specificity of 0.63 to differentiate endometriosis cases from controls." (PMID 30969738, 2019).